SNAI1 (snail family transcriptional repressor 1)
Diseases named in the same sentence as SNAI1 in open-access papers (continued):
Sharing a sentence is not in itself a finding about the gene and the disease.
ovarian carcinoma (continued). "OC-MQs increased mesenchymal markers’ expression, including SNAI1, CDH2, FN, VIM, and ZEB1, in ovarian cancer cells." (PMID 39937005, 2025). "SNAI2/Slug, and SNAI1/Snail have been reported to be upregulated by treatment with TGF-β and BMP as well as by treating ovarian cancer cells with IL-17, chemokine CCL5, and CCL19/CXCR7." (PMID 36766756, 2023). "EMT TFs such as SNAI1/2, ZEB, and TWIST have been reported to be upregulated in ovarian cancer cell lines when treated with various cytokines." (PMID 36766756, 2023). "Especially, with regard to EMT process, several articles demonstrated the important roles of m6A regulation on SNAI1 in HeLa and HepG2 cells, GFI1 and ZMYM1 in gastric cancer cells, AXL in ovarian cancer cells, and ZBTB1 in bronchial epithelial cells." (PMID 36183833, 2022). "CXCR7 overexpression not only significantly enhances histone modification and transcription, but also indirectly induces the expression of mesenchymal markers such as SNAI1, SNAI2, and CDH2 to promote migration and invasion of ovarian cancer cells." (PMID 33829065, 2021). "The intermediate E ovarian carcinoma cell lines exhibit significantly higher levels of SNAI1 mRNA and lower levels of ZEB1/2 mRNAs relative to the intermediate M ovarian carcinoma cell lines." (PMID 31121840, 2019). "By using an in-house panel of ovarian cancer cell lines, SGOCL, we firstly investigated the SNAI1 and SNAI2 mRNA expression and protein abundance." (PMID 31165775, 2019). "In an ovarian cancer cell lines panel, we identified that SNAI1 and SNAI2 expressions were mutually exclusive, where SNAI1 predominantly represses SNAI2 expression." (PMID 31165775, 2019). "Among which, SNAI1 and SNAI2 were efficiently induced during EMT and their expressions were correlated with poor clinical outcome in patients with breast, colon and ovarian carcinoma." (PMID 31165775, 2019). "Meanwhile, we try to explore the potential link between SNAI1, SNAI2, and LVSI status in ovarian cancer using data from The Cancer Genome Atlas (TCGA) database." (PMID 28039463, 2017). "We also analyze the pair of human ovarian cancer cells, OVCA433-GFP (control) and OVCA433 that overexpresses SNAI1=Snail (OVCA433-Snail) that has undergone epithelial-to-mesenchymal transition (EMT)." (PMID 26626154, 2015). "Interestingly, TWIST1 has been reported to regulate DDR2 expression in ovarian cancer and was found to be a shared effector of FOXQ1 and SNAI1 in this study." (PMID 36713812, 2022). "Furthermore, Snai1, a transcription factor that works as a master regulator of the epithelial/mesenchymal transition process (EMT) is involved in ovarian cancer resistance and progression." (PMID 31863638, 2020). "Our previous study showed that ovarian cancer cells induced to have mesenchymal phenotype either by overexpression of EMT transcription factors (ZEB1, SNAI1, and SNAI2), oncogenes (H-Ras v12), or by drug resistance were all consistently more deformable than cells with epithelial phenotype." (PMID 33330495, 2020). "Using breast, pancreatic, and ovarian cancer cells, transforming growth factor beta-1 (TGFB1) or epidermal growth factor (EGF) treatment or SNAI1 overexpression increased stemness and reduced let-7 expression, while SNAI1 knockdown reduced stemness and increased let-7 expression." (PMID 33806868, 2021). "Many of the other EMT-related transcription factors, such as SNAI2, TWIST1, and ZEB1 are often overexpressed in the MAF signature, but SNAI1 is not (and, at least in ovarian carcinoma in which we have methylation data, this is due to its differentially methylated status)." (PMID 21047417, 2010). "TGFB1 does not induce SNAI1 expression in OVSAHO or OVCAR8; for this reason, ovarian cancer cell lines were treated with EGF." (PMID 33806868, 2021).
ovarian carcinoma (continued). "In the ovarian cancer tissues, further significant positive correlations were observed between DAB2 and CSC markers (CD34, ALDH1A1, CD117 (Kit)) and mesenchymal markers (MMP9, SNAI1 and MMP3) and negative correlations with mesenchymal markers (CDH2, FOXC2 and SOX10)." (PMID 37815603, 2023).
gastric cancer (82 papers, 2012 to 2026). A primary or metastatic malignant neoplasm involving the stomach. "Possible interactions between FIRΔexon2 and FBW7 caused the FBW7’s disability to further destabilize Snai1 proteins and resulted in decreased E-cadherin levels that promoted gastric cancers through EMT." (PMID 32071290, 2020). "On the other hand, it was recently reported that Scp1 stabilizes the zinc-finger type transcription factor SNAI1 (Snail), a known inducer of the epithelial–mesenchymal transition that promotes cancer metastasis and invasion in gastric cancer." (PMID 38612548, 2024). "The analysis of various gastric cancer cell lines and gastric cancer patient samples also revealed a positive association between ELK3 and BMP1, LOXL2, SNAI1, SERPINF1, DCN, and NID1, and these genes were associated with a poor prognosis." (PMID 35409069, 2022). "TRERNA1 is highly expressed in gastric cancer, and it enhances the expression of SNAI1 to increase epithelial-mesenchymal transition, thereby promoting tumor metastasis." (PMID 35034562, 2022). "In tumors, high expression of FGF8 affects EMT through the BRG1/Snai1/E-cadherin pathway and promotes tumor proliferation and invasion of gastric cancer." (PMID 34526059, 2021). "Correlation of SNAI1 mRNA expression and clinical prognosis in gastric cancer with different clinicopathological factors by Kaplan-Meier plotter (GSE62254, GSE14210, GSE15459, GSE22377, GSE29272, GSE51105)." (PMID 32833672, 2020). "Together, FIRΔexon2 engages in multi-step post-transcriptional regulation of BRG1, affecting EMT through the BRG1/Snai1/E-cadherin pathway and promoting tumor proliferation and invasion of gastric cancers." (PMID 32071290, 2020). "SNAI1 has a certain value in evaluating the disease progression and survival prognosis of patients with gastric cancer." (PMID 32833672, 2020). "Collectively, this study proposed that FIRΔexon2 engages in multi-step post-transcriptional regulation of BRG1, affecting EMT through the BRG1/Snai1/E-cadherin pathway and promoting tumor proliferation and invasion of gastric cancers." (PMID 32071290, 2020). "Together, E-cadherin suppression by FIRΔexon2 at least partly via the FBW7/BRG1/Snai1 axis was shown to promote invasion of gastric cancer cells." (PMID 32071290, 2020). "Snai1 expression was increased but BRG1 was decreased in (T) than those in (N) in human gastric cancer tissues." (PMID 32071290, 2020). "Resveratrol and cyclopamine treatment upregulated E-cadherin and downregulated GLI1, SNAI1 and N-cadherin in gastric cancer cell line." (PMID 31547193, 2019). "USP47, RAB22A, SIRT1, Snai1, and so forth are targets of miR-204 that mediate miR-204 reducing the oncogenicity of gastric cancer." (PMID 28133610, 2017). "miR-153, as an independent prognostic marker for predicting survival of gastric cancer patients, is downregulated in GC and promote gastric cancer cell migration and invasion, by inhibiting SNAI1-induced EMT." (PMID 26576674, 2015). "SNAI1 drives stem cell properties, metabolic alterations, cancer invasion, and chemoresistance in epithelial ovarian cancer, promotes metastasis in breast tumors, and high expression of SNAI1 is considered a clinical biomarker in gastric cancer." (PMID 40613523, 2025). "A recent report suggested that USP37-mediated deubiquitination of SNAI1 could promote the proliferation and migration of gastric cancer cells." (PMID 36768307, 2023). "PCGEM1 promotes gastric cancer metastasis and invasion by regulating SNAI1." (PMID 35109849, 2022). "Simultaneously, high expression of SNAI1 correlates with clinical relevance of gastric cancer." (PMID 32833672, 2020). "In addition, other miR-153 downstream transcripts, such as SNAI1 or KLF5 were reported to be involved in functional modulations in gastric cancer." (PMID 32849774, 2020).
gastric cancer (continued). "In cell experiment, it was also found that up-regulation and inhibition of SNAI1 expression could enhance and inhibit the migration and invasion ability of gastric cancer cells in vitro, respectively." (PMID 32833672, 2020). "Getting together, in miR-204 regulation pathway, USP47, RAB22A, SIRT1, Snai1, and so forth and SOX4 may play an associating role contributing to gastric cancer progressing." (PMID 28133610, 2017). "Similar results were obtained in gastric cancer where miR-153 was able to suppress migration and invasion by inhibiting SNAI1-induced EMT and also serve as an independent prognostic marker for predicting survival of gastric cancer patients as was the case in pancreatic ductal adenocarcinoma (PDAC)." (PMID 26784241, 2016). "Zyxin reduces gastric cancer cell stemness and EMT by inhibiting the acetylation level of histone H3 K9 and K23, resulting in the downregulation of SNAI1/2." (PMID 37667739, 2023). "The gene analysis of samples from patients with gastric cancer indicated that a high ELK3 expression is positively correlated with BMP1, LOXL2, SNAI1, SERPINF1, DCN, and NID1 expression, all of which are closely associated with a poor prognosis." (PMID 35409069, 2022). "First, the correlation between ELK3 expression and BMP1, LOXL2, SNAI1, SERPINF1, DCN, and NID1 expression was analyzed in 19 different gastric cancer cell lines." (PMID 35409069, 2022). "Notably, the analysis of patients with gastric cancer indicated the marked positive regulation of ELK3 and BMP1, LOXL2, SNAI1, SERPINF1, DCN, and NID1 gene expression, suggesting a significant positive correlation between ELK3 and ECM remodeling-associated genes in gastric cancer." (PMID 35409069, 2022). "Patients with gastric cancer with a high expression of BMP1, LOXL2, SNAI1, SERPINF1, DCN, and NID1 had a poor prognosis." (PMID 35409069, 2022). "In gastric cancer, visfatin facilitates cell migratory and invasive abilities, as well as the EMT process, by targeting the SNAIL transcription factor SNAI1 via NF-κB signaling." (PMID 34445345, 2021). "FIR family (FIR, FIRΔexon2, and PUF60), Snai1, and BRG1 increased, but FBW7 and E-cadherin decreased in human gastric cancers, as shown by immunohistochemical staining; however, the expression of BRG1 was reduced in some cases." (PMID 32071290, 2020). "In human gastric cancer cells, a pre-treatment with N-acetylcysteine attenuated the Helicobacter pylori-induced activation of ERK and SNAI1 promoter activity." (PMID 31141910, 2019). "Previous studies showed that miR-204 suppressed gastric cancer through targeting USP47, RAB22A, SIRT1, Snai1, and so forth." (PMID 28133610, 2017). "The results showed that EMT‐promoting factors SNAI1 and SNAI2 were significantly downregulated, while EMT repressors GRHL2 and OVOL1 were significantly upregulated, suggesting that zyxin negatively regulates EMT in gastric cancer cells." (PMID 37667739, 2023). "The expression of MYC proto-oncogene, as well as bHLH transcription factor (MYC) and its target, snail family transcriptional repressor 1 (SNAI1), is inhibited when circ-TNPO3 sequesters IGF2BP3, which reduces the ability of gastric cancer cells to proliferate and metastasize." (PMID 38003674, 2023). "The SNAI1 gene also exhibited a higher expression in the gastric cancer samples, although this increase was not statistically significant." (PMID 35409069, 2022). "Therefore, FIRΔexon2 appears to suppress E-cadherin expression at least in part through the FBW7/BRG1/Snai1 axis for promoting EMT and invasion in gastric cancer." (PMID 32071290, 2020). "The ELK3 expression in gastric cancer cells and human gastric cancer samples positively correlated with that of BMP1, LOXL2, SNAI1, SERPINF1, DCN, and NID1, suggesting that this gene signature may be predictive molecular markers for aggressive gastric cancer progression." (PMID 35409069, 2022).
gastric cancer (continued). "In addition, studies have found that cyclooxygenase-2 COX-2) can regulate the expression of E-cad in gastric cancer by affecting nuclear factor κB and SNAI1 pathway, which is also one of the mechanisms of COX-2 regulating the invasion and metastasis of gastric cancer." (PMID 32833672, 2020). "The expression of BRG1 was not necessarily increased nor positively correlated with Snai1 in some human cancers, which indicated that the FBW7/BRG1/Snai1 axis is perturbed in gastric cancers." (PMID 32071290, 2020). "The simultaneous increases in BRG1, Snai1, and E-cadherin did not induce EMT in Gan-mice; however, the expressions of FBW7, BRG1, and E-cadherin decreased in the human gastric cancer tissues." (PMID 32071290, 2020).
hepatocellular carcinoma (79 papers, 2011 to 2025). A malignant tumor that arises from hepatocytes. "In hepatocellular carcinoma, miR-203 and miR-502-5p commonly target SNAI1, an EMT-promoting factor, and they are sponged by circ_ZNF652; therefore, lung metastasis is provoked by circ_ZNF652." (PMID 35055115, 2022). "Compared with control treatment, treatment with CCL8 triggered the migration of HepG2 hepatoma cells, substantially increased their levels of vimentin and SNAI1 expression, and downregulated their levels of E-cadherin expression." (PMID 35362480, 2022). "In particular, we focused on TEM7 for its characterized role in bevacizumab-induced infiltrative growth of GBM and on SNAI gene family due to the role of SNAI1 gene in modulating EMT upon regorafenib treatment of hepatocellular carcinoma cells." (PMID 36551679, 2022). "In this study, Panx1 was found to promote the transmembrane transformation of hepatocellular carcinoma cells by promoting the expression of Snai1, an EMT-related transcription factor." (PMID 31737105, 2019). "In conclusion, our findings revealed that SNAI1 is involved in the development of hepatocellular carcinoma via regulating the growth and apoptosis of tumor cells." (PMID 27239445, 2016). "We also observed that SNAI1 expression was correlated with distal metastasis, incomplete tumor capsule formation, and histological differentiation in hepatocellular carcinoma (HCC)." (PMID 27239445, 2016). "In this study, we investigated the effects and mechanisms of SNAI1 in the proliferation and apoptosis of hepatocellular carcinoma using clinical samples and cell lines." (PMID 27239445, 2016). "miR-30 family also inhibits cell migration, invasiveness, and metastasis in vitro in other tumors, such as lung, breast, and hepatocellular cancer, by targeting SNAI1 and Vimentin." (PMID 25409297, 2014). "Besides these, other reports have described additional miRNAs as also repressing SNAI1 mRNA in other systems: miR-211-5p in renal cancer and miR-122 in hepatocellular carcinoma." (PMID 31141910, 2019). "The results of our previous study also revealed that TRERNA1 promotes hepatocellular carcinoma (HCC) metastasis via recruitment of the EHMT2/SNAI1 complex to suppress CDH1." (PMID 35031597, 2022). "On the contrary, LINC01133 facilitates EMT via enhancing SNAI1 levels and activates STAT3 signaling in hepatocellular carcinoma." (PMID 35055115, 2022). "In glioblastoma and hepatocellular carcinoma, a hypoxic microenvironment maintains stem cells or promotes reprogramming towards a CSC phenotype, i.e., by inducing EMT via activation of SNAI1 through HIF-1α." (PMID 34771704, 2021). "In hepatoma cells, phosphorylated STAT3 was also found to bind to the SNAI1 promoter; inhibition of STAT3 abrogated the hepatitis virus C core-induced Snail1 expression." (PMID 31141910, 2019). "In HCCLM3 hepatocellular carcinoma cells, downregulation of AGO1 decreases Smad4 binding to SNAI1 promoter and reduces its transcription." (PMID 31141910, 2019). "Regulation of the mesenchyme-specific transcription factor gene Snail (SNAI1), which is activated via the HIF-1α signaling cascade, enhances expression of the mesenchymal markers β-catenin and vimentin in hepatocellular carcinoma in response to hypoxia." (PMID 26528854, 2015). "In hepatocellular carcinoma, researchers discovered that METTL3 could catalyze m6A modification in CDS and 3’UTR of SNAI1 mRNA, and YTHDF1 tended to bind to m6A in CDS of SNAI1 to mediate translation." (PMID 36830614, 2023). "Moreover, FOXS1 induced by TGFβ promoted a classical model of EMT by activating the expression of EMT-transcription factors (SNAI1, and SNAI2) in hepatocellular carcinoma." (PMID 35898871, 2022). "Additionally, in HCCLM3 hepatocellular carcinoma cells, the isoprenoid antibiotic ascochlorin increased the sensitivity to doxorubicin treatment by directly inhibiting binding of STAT3 to SNAI1 promoter." (PMID 31141910, 2019).
hepatocellular carcinoma (continued). "In hepatocellular carcinoma, miR-153 inhibits EMT by targeting SNAI1." (PMID 31141910, 2019). "One possible role of Snai1 in neoangiogenesis may rely on the vascular pattern which is independent of EMT in hepatocellular carcinoma." (PMID 30975732, 2019). "However, the possible functions of SNAI1 in the proliferation and apoptosis of hepatocellular carcinoma have not been clearly identified." (PMID 27239445, 2016).